DLL1 (delta like canonical Notch ligand 1)
Diseases named in the same sentence as DLL1 in open-access papers (continued):
Sharing a sentence is not in itself a finding about the gene and the disease.
breast carcinoma (continued). "Together, our data reveal for the first time the subtype-specific function of DLL1 in promoting tumor growth, progression, and metastasis of ERα+ luminal breast cancer." (PMID 30442981, 2019). "Genetic studies show that DLL1-mediated Notch signaling in breast cancer is important for tumor cell proliferation, angiogenesis, and cancer stem cell function." (PMID 30442981, 2019). "Overall, our study demonstrates for the first time that the Notch ligand DLL1 is overexpressed in ERα+ luminal breast cancer." (PMID 30442981, 2019). "In support, knockdown of DLL1 in ERα+ luminal breast cancer cells reduces primary tumor growth and metastasis in ERα+ tumors, but not in tumors of the TNBC/basal subtype." (PMID 30442981, 2019). "E2 treatment of an additional luminal breast cancer cell line, T47D showed a similar increase in DLL1 expression over time." (PMID 30442981, 2019). "Together, our results highlight an unexpected and novel subtype-specific function of DLL1 in promoting luminal breast cancer that is regulated by estrogen signaling." (PMID 30442981, 2019). "In this study, we identify the Notch ligand DLL1 as a potential therapeutic target for ERα+ luminal breast cancer." (PMID 30442981, 2019). "Future studies will delineate if resistance and relapse in ERα+ breast cancers is dependent on DLL1-mediated Notch signaling, as such studies would aid in developing novel therapies for ERα+ luminal breast cancer patients." (PMID 30442981, 2019). "Together, our findings highlight a novel subtype-specific function of DLL1-driven Notch signaling as a potential target for therapeutic intervention for this large subset of breast cancer patients." (PMID 30442981, 2019). "In tumors such as breast cancer, various members of the Notch pathway, including Notch1, Notch3, DLL1, and DLL3, have been implicated in either promoting or inhibiting angiogenesis." (PMID 40486870, 2025). "Previous research reported that a high level of estrogen could protect Dll1 from the ubiquitin proteasomal degradation pathway in breast cancer." (PMID 37833248, 2023). "Increased DLL1 expression was correlated with better survival in breast cancer." (PMID 36476410, 2022). "Similar research published in 2021 reported that Delta like 1 (DLL1) could promote the responsiveness of breast cancer and lung cancer to immunotherapy by mediating the normalization of tumor blood vessels and the polarization of M1-like macrophages." (PMID 36699464, 2022). "Our data showed that LNT combined with DLL1 reduced tumor volume of breast cancer and lung cancer." (PMID 36008793, 2022). "Finally, pharmacological blocking of Dll1 or NF-κB pathway completely sensitizes Dll1+ tumors to chemotherapy, highlighting therapeutic avenues for chemotherapy resistant breast cancer patients in the near future." (PMID 33462238, 2021). "As such, targeting Dll1 in combination with chemotherapy and NF-κB may be a promising therapeutic strategy for breast cancer patients who are resistant to chemotherapy." (PMID 33462238, 2021). "Similarly, the Dll1, Jag1 mediated survival is responsible for chemoresistance in breast cancer and multiple myeloma." (PMID 33968932, 2021). "Collectively, our studies from Dll1 conditional knockout and reporter mice suggest that Dll1 may be a critical determinant of metastasis in breast cancer." (PMID 33462238, 2021). "Together, our data suggest that Dll1-mediated Notch signaling drives metastasis and chemoresistance and may therefore be responsible for higher mortality in breast cancer." (PMID 33462238, 2021). "As metastasis is associated with increased cancer stem-like cells that is associated with increased dissemination of cells from the primary tumor site to distant metastatic sites, we next assessed the role of DLL1 in these additional functions in luminal breast cancer." (PMID 30442981, 2019).
breast carcinoma (continued). "Altogether, our data suggest a protumor function of Notch ligand DLL1 in non-TNBC/luminal breast cancer, which is associated with worse prognosis/survival in the patient samples." (PMID 30442981, 2019). "Importantly, our data indicate that the presence of CSCs in tamoxifen-sensitive ERα+ luminal breast cancer is dependent on DLL1-mediated Notch signaling." (PMID 30442981, 2019). "Based on these evidences, and on the observation that DLL1 expression is generally increased in human breast cancers when compared to normal breast tissues, we reasoned that DLL1 could play a role in the tumorigenic process of BC." (PMID 31107884, 2019). "In addition, high DLL1 expression (DLL1high) correlates with decreased distant metastasis-free survival (DMFS) of ERα+ luminal breast cancer patients." (PMID 30442981, 2019). "In our hands, we find that estrogen-induced stabilization of DLL1 protein may facilitate luminal cancer progression with important implications for the treatment of ERα+ breast cancer patients." (PMID 30442981, 2019). "Our data show that loss of DLL1 reduces CSC number and function in luminal breast cancer cells." (PMID 30442981, 2019). "To investigate the clinical significance of DLL1 in breast cancer, we assessed DLL1 protein expression by performing IHC on primary human patient samples (TNBC patients n = 58, non-TNBC patients n = 60, and adjacent normal tissue n = 23) using an anti-DLL1 antibody." (PMID 30442981, 2019). "Indeed, endogenous expression of miR-34a correlates with down-regulation of Dll1 in other, different, tumor types and cell lines, such as for example, breast cancer cells." (PMID 21931765, 2011). "The Notch signaling system that contains four Notch receptors (Notch1- Notch4) and five canonical ligands (Dll1, Dll3, Dll4, Jagged1 and Jagged2), plays important roles including carcinogenesis, cancer stem cell renewal, angiogenesis, and chemotherapy resistance in the progression of breast cancer." (PMID 33413403, 2021). "Therefore, targeting of Dll1 combined with chemotherapy may be an effective strategy for the treatment of breast cancer chemoresistance." (PMID 34374886, 2021). "Furthermore, when DLL1 expression was compared with DMFS in four different molecular subtypes of breast cancer, higher DLL1 levels strongly correlated with poor patient outcome in the ERα+ Luminal A subtype, but not in the ERαlow subtypes such as luminal B, TNBC/basal, and HER2." (PMID 30442981, 2019). "Thus, Dll1 may enhance both proliferation and angiogenesis to promote tumor formation and progression of ERα+ luminal breast cancer." (PMID 30442981, 2019). "Finally, overexpression of Dll1 leads to more tumor growth and increased metastasis, confirming that DLL1 expression strongly influences the growth of primary tumors and metastasis in ERα+ luminal breast cancer." (PMID 30442981, 2019). "However, the function of Dll1 in breast cancer remains elusive." (PMID 30442981, 2019). "On the other hand, TCF7L2, ARRB1, DLL1, FZD7, HES1, and JAG1 transcript levels were significantly lower in breast cancer tissues than in normal samples (p < 0.0009, p = 0.0131, p = < 0.0001, p = < 0.0001, p = 0.0138, and p < 0.0001, respectively)." (PMID 36476410, 2022). "We further showed that Dll1 is preferentially upregulated in luminal breast cancer compared to TNBC/basal cancer and regulates CSC function in these breast cancer cells." (PMID 33462238, 2021). "The knock-down of DLL1 reduces the expression of CD24 and CD44, which is the biomarker of breast cancer CSCs, and down-regulates both tumor growth and lung metastasis of luminal breast cancer." (PMID 34098945, 2021). "In this study, we show that Dll1 is essential for tumor development and metastasis in an Polyoma Middle T (MMTV-PyMT) mammary tumor mouse model." (PMID 33462238, 2021).
breast carcinoma (continued). "It was also reported that miR-34a inhibits proliferation, migration, and invasion of breast cancer cells by targeting several genes including E2F3, CD44, and SIRT1, Notch1 and DLL1." (PMID 25826085, 2015). "Both MCF7 DLL1 knockdowns (KD1 and KD2) exhibited reduced primary tumor growth in NSG mice compared to control cells (that received an empty shRNA vector), corroborating observations in human patients with ER+ breast cancer." (PMID 30442981, 2019). "Our IHC analyses revealed significantly higher levels of DLL1 protein expression in the luminal/non-TNBC subtype compared to either normal cells or TNBC/basal breast cancer samples (p < 0.0001)." (PMID 30442981, 2019). "Intriguingly, DLL1 overexpression correlates with poor prognosis in ERα+ luminal breast cancer, but not in other subtypes of breast cancer." (PMID 30442981, 2019). "Furthermore, Dll1+ breast cancer cells were shown to recruit CAFs in an IL-6-dependent fashion and to promote Wnt ligand secretion by NOTCH2/3-expressing CAFs resulting in Wnt/β-catenin–dependent increase in Dll1+CSCs to promote metastasis." (PMID 37460910, 2023). "Thus, Kumar and coworkers showed that DLL1, but not other NOTCH ligands (DLL3, JAGGED1, and JAGGED 3), is overexpressed in ER+ luminal breast cancers: in these tumors, DLL1 overexpression correlates with poor prognosis." (PMID 32210163, 2020).
glioma (19 papers, 2011 to 2024). A benign or malignant brain and spinal cord tumor that arises from glial cells (astrocytes, oligodendrocytes, ependymal cells). "DLL1 overexpression mitigated the reduction in glioma cell viability and invasion caused by VANGL2 knockdown compared to control groups." (PMID 39871948, 2024). "For example, DLL1 expression is significantly higher in oligodendrogliomas than in normal brain cells and is associated with glioma cell proliferation and survival." (PMID 31107884, 2019). "Various studies have demonstrated increased expression of distinct components of Notch signaling pathway (such as Notch1, Notch2, Dll1, Dll4 and Jag1) and Notch target genes (Hey1, Hey2, Hes1) in glioma cell lines or primary human glioma samples including GBM." (PMID 36010607, 2022). "Similar to other cancer types such as glioma and multiple myeloma, these findings suggest that DLL1 contributes to the carcinogenic features of MCF-7 cells by promoting cell proliferation and survival." (PMID 31107884, 2019). "DLL1 has been reported to be critical for proliferation in some cancer cells, such as glioma and melanoma cells." (PMID 31107884, 2019). "In this study, we pointed out that DLL1 was required for Notch activity to maintain glioma stem cell phenotype." (PMID 28380416, 2017). "To date, it has been shown that Notch1 and its ligands, Dll1 and Jag1, are overexpressed in many glioma cell lines and primary human gliomas." (PMID 28950865, 2017). "It has been shown that Notch1 and its ligands, Dll1 and Jag1, are overexpressed in many glioma cell lines and primary human gliomas." (PMID 28950865, 2017). "Down-regulation of Notch1, Dll1, or Jag1 by RNA interference induces apoptosis and inhibits proliferation in multiple glioma cell lines." (PMID 28950865, 2017). "Although our model provides a new theoretical framework to investigate the effects of Dll1, Jag1 and Fringe in the Notch1 signaling system in glioma cells, it ignores the spatial effects which can be also important." (PMID 28950865, 2017). "There is some precedence for a positive regulatory loop in which Notch regulates the expression of ligands, including Jag1 in NIH 3T3 cells and Dll1 in glioma cells." (PMID 21352545, 2011). "Notch1 and its ligands, Dll1 and Jagged1, were overexpressed in many glioma cell lines and primary human gliomas." (PMID 21342503, 2011). "When the expression of Notch1, Dll1 or Jagged1 was down-regulated by RNA interference, apoptosis and proliferation inhibition in multiple glioma cell lines were induced." (PMID 21342503, 2011). "The frequency of these mutations is perhaps surprising since higher expression of ASCL1, Dll1, Notch1, -3, -4 have been shown to correlate with a higher glioma grade and poorer prognosis, implicating Notch signaling in more undifferentiated and aggressive tumor phenotypes." (PMID 31995621, 2020). "Reports have shown that knocking down the NOTCH ligands Jagged1 or Dll1 by RNA interference reduced survival and growth of tumor cells in multiple glioma cell lines and high Jagged1 expression correlates with poor prognosis of glioma patients." (PMID 33076453, 2020). "Besides Fringe, Dll1 and Jag1 also play critical roles in glioma cell fate decisions due to combinatorial effects between them." (PMID 28950865, 2017). "The purpose of this paper is to present a computational model for Notch1 signaling pathway in glioma cell lines and primary human gliomas based on intertwined dynamics with cis-inhibition and trans-activation involving the proteins Notch1, Dll1, Jag1, and Lunatic Fringe." (PMID 28950865, 2017). "In this study, we showed that DLL1 was important on maintaining glioma stem cell phenotype." (PMID 28380416, 2017). "Furthermore, down-regulation of NOTCH1 and its ligand DLL1 has been reported to inhibit tumor proliferation in glioma cell lines, which may play the function of promoting tumor proliferation." (PMID 31118022, 2019).
glioma (continued). "Many of them, such as CDHR1, DLL1, DLL3 and SCG3, have been reported to be potential therapeutic targets for glioma treatment." (PMID 35456975, 2022). "Next, we demonstrated that transcript levels of NOTCH pathway members NOTCH1, NOTCH4, DLL1 and HES-1, which carry METTL3-dependent m6A peaks, were downregulated in METTL3-silenced glioma cells." (PMID 30781903, 2019). "ShRNA targeting Notch ligand Delta-like 1 (DLL1) decreased CD133 and Nestin expression, and impaired the self-renewal ability of CD133+ U87-MG and U251-MG glioma cells, indicating DLL1/Notch1 signaling promoted stem cell phenotype maintenance." (PMID 28380416, 2017). "KALRN, EIF1AD, DLL1, SH3RF1, and TLN1 are involved in neuronal structural integrity, plasticity, differentiation, and may contribute to the highly invasive nature of GBM as compared to other gliomas." (PMID 36834486, 2023). "These in vitro data suggest that Notch1 acts as an oncogene in glioma, which has been confirmed in an intracranial xenograft model, where mice injected with control U251MG cells died sooner as compared to mice that received cells in which Notch1 or Dll1 were downregulated by siRNA." (PMID 25601901, 2014). "Expressions of candidates such as AFP, DLL1, and GRB14 were non-significant compared to normal samples; however, they were highly significant across different gliomas." (PMID 36834486, 2023). "Silencing DLL1 in the Arp2/3 inhibited CD133+ cells did not further abrogate the stem cell phenotype, suggesting DLL1 function requires Arp2/3 complex in glioma initiating cells (GICs)." (PMID 28380416, 2017).
Sepsis (11 papers, 2019 to 2026). Sepsis is defined as life-threatening organ dysfunction caused by a dysregulated host response to infection. "DLL1 showed significant diagnostic performance for differentiating sepsis (area under the curve (AUC) 0.746; CI 0.685–0.807) from non-septic infections and inflammatory diseases." (PMID 37298115, 2023). "The results of the present analysis support these findings and show that the measurement of DLL1 provides additional diagnostic value to distinguish sepsis from chronic-inflammatory diseases." (PMID 37298115, 2023). "DLL1 is further involved in sepsis-induced endothelial damage leading to a loss of its barrier function." (PMID 35922468, 2022). "Next, we investigated the value of DLL1 as a diagnostic marker for the differentiation between sterile inflammation and sepsis." (PMID 31396491, 2019). "We aimed to unravel the kinetic of DLL1 and its diagnostic value as a host-derived response biomarker to discriminate sepsis from sterile systemic inflammatory processes compared to established markers." (PMID 31396491, 2019). "The diagnostic potential of DLL1 has successfully been demonstrated in sepsis research." (PMID 37298115, 2023). "Further studies need to unravel the association between DLL1 and kidney function during sepsis." (PMID 31396491, 2019). "Recent studies have explored novel biomarkers such as host-derived delta-like canonical notch ligand 1 (DLL1), which showed superior performance for sepsis recognition compared to PCT in some contexts." (PMID 41409941, 2025). "Further prospective studies are necessary to evaluate DLL1 as a biomarker for systemic infections and sepsis in different cohorts of critically ill patients in the intensive care unit and emergency department." (PMID 37298115, 2023). "Patients of the sepsis group showed significantly elevated plasma DLL1 levels compared to patients with uncomplicated infections and sterile inflammation." (PMID 37298115, 2023). "Prospective validation of DLL1 as a sepsis biomarker in larger cohorts is warranted to support the robustness of the promising results to date." (PMID 37298115, 2023). "DLL1 demonstrated promising results for diagnosing sepsis and was able to differentiate sepsis from other infectious and inflammatory diseases." (PMID 37298115, 2023). "In particular, the interaction of DLL1 and human monocytes during in vitro bacterial infections raised interest in its use as a biomarker for infection, and consequently, for sepsis." (PMID 35922468, 2022). "In fact, dengue virus infection has been shown to induce upregulation of DLL1 although to a less extent than observed in sepsis." (PMID 34955884, 2021). "Notch ligand DLL1 has been found in the plasma of sepsis patients and the soluble form of DLL1 was observed in cell supernatants of human monocytes." (PMID 34336718, 2021). "In patients with sepsis, the elevation of the soluble Notch ligand DLL1 in the blood is particularly pronounced." (PMID 34955884, 2021). "As DLL1 is the Notch ligand that is highly upregulated in patients with sepsis, we concentrated on this ligand." (PMID 34955884, 2021). "The Notch signaling pathway highly impacts development as well as stability of the vascular, and the Notch ligand DLL1 is highly upregulated in patients with sepsis." (PMID 34955884, 2021). "In summary, DLL1 is increased exclusively in sepsis, while sterile insults as major surgery and severe trauma do not influence its generation." (PMID 31396491, 2019). "As these conditions are well-known to induce sterile inflammatory responses of the body, DLL1 represents a robust and specific biomarker for sepsis." (PMID 31396491, 2019). "During sepsis, DLL1 enhances endothelial dysfunction and vascular leakage." (PMID 38502427, 2024). "Therefore, we measured DLL1 in plasma samples of prospective cohorts with sepsis, signs of infection in the emergency department, bacterial skin infection with Staphylococcus aureus, Hidradenitis Suppurativa, and inflammatory bowel disease." (PMID 37298115, 2023).